PTBP1 (polypyrimidine tract binding protein 1)
Diseases named in the same sentence as PTBP1 in open-access papers (continued):
Sharing a sentence is not in itself a finding about the gene and the disease.
glioma (continued). "PTBP1 has been described as one of the key RBPs in regulating AS in neural development and known oncogenic AS gene isoforms such as PKM and USP5 in glioma." (PMID 38662454, 2024). "Analysis of upstream RNA binding proteins reveals PTBP1 as a key regulator of the AS signature where targeting of PTBP1 suppresses tumor growth and promotes the expression of a neuron marker TUJ1 in glioma stem-like cells." (PMID 38662454, 2024). "A previous study has documented a connection between elevated PTBP1 expression levels and the WHO grade in glioma." (PMID 37808305, 2023). "SRSF3 has been shown to interact with two additional splicing factors, polypyrimidine tract binding protein 1 (PTBP1), and polypyrimidine tract binding protein 2 (PTBP2), which promote glioma cell motility." (PMID 35883576, 2022). "This study aimed to demonstrate the role of the PTBP1/circRNA_001160/miR-195-5p/ETV1 pathway in regulating BTB permeability, which can provide a new strategy for the comprehensive treatment for glioma." (PMID 31862871, 2019). "Our results demonstrated that the PTBP1/circRNA_001160/miR-195-5p/ETV1 axis was critical in the regulation of BTB permeability and provided new targets for the treatment of glioma." (PMID 31862871, 2019). "Firstly, the endogenous expressions of PTBP1, circRNA_001160, miR-195-5p and ETV1 in astrocyte endothelial cells (AECs) and glioma endothelial cells (GECs) were detected." (PMID 31862871, 2019). "The present study showed that the combined application of PTBP1, circRNA_001160, and miR-195-5p with the anti-tumor drug Dox effectively promoted Dox through BTB and extremely induced the apoptosis of glioma cells." (PMID 31862871, 2019). "It was discovered that reduction of PTBP1 and PTBP2 induced glioma cells to decrease proliferation and migration and to increase cell adhesion." (PMID 29936497, 2018). "For example, lower amounts than expected regarding mRNA levels are noted for MDH1 in GBM and SIRT1 in gliomas; or the protein concentration was increased in glioma tissues, although the mRNA was only slightly modified (typically CCPG1, BCL2, MDM2 and PTBP1)." (PMID 21655185, 2011). "PTBP1 (polypyrimidine tract-binding protein 1) is known to be a key RNA-binding protein (RBP) in regulating AS under normal and pathological conditions such as in glioma." (PMID 39915450, 2025). "We have observed heterozygous amplification of IFI30 and PTBP1, suggesting that their CNV may have the potential to modify the immune infiltration status of glioma patients to a certain degree." (PMID 41438761, 2025). "Furthermore, rescue experiments validated that PLOD3 is the functional target of circ_003137/PTBP1, thus regulating EMT of glioma cells." (PMID 39431006, 2024). "PTBP1 protein was highly expressed in glioma tissues (79/150, 52.7%), but no expression was detected in normal brain tissues (0/20, 0%) in our cohort." (PMID 35299889, 2022). "In our tumor samples, intense positive nuclear staining was observed in high-grade glioma, particularly in GBM, indicating strong upregulation of PTBP1 expression in tumor cells of glial suggests involvement of this protein in cellular malignant transformation." (PMID 35299889, 2022). "Out of the 150 malignant glioma tissues (60 LGG and 90 GBMs) and 20 normal brain tissues in our cohort, PTBP1 protein was high expressed in glioma tissues (79/150, 52.7%), but no expression was detected in normal brain tissues (0/20, 0%)." (PMID 35299889, 2022). "PTBP1 promotes the expression conversion of two pyruvate kinases PKM1 and PKM2, and enhances the aerobic glycolysis of cells, thereby promoting the proliferation of glioma cells." (PMID 31862871, 2019). "Interestingly, SRSF3 is known to interplay with two other splicing factors, polypyrimidine tract binding protein 1 (PTBP1) and polypyrimidine tract binding protein 2 (PTBP2), that positively regulate glioma cells migration." (PMID 29415469, 2018).
glioma (continued). "They identified four splicing factors (SRSF3, RBM22, PTBP1, and RBM3) that could accurately distinguish between tumor samples and control samples, as well as different subtypes of tumors from mouse models with gliomas." (PMID 39915450, 2025). "However, given the relatively low hazard ratio (between 1.0 and 1.01) in the latter two datasets, we do not consider PTBP1 a reliable independent prognostic factor for glioma." (PMID 38918441, 2024). "There is no study on the expression of PTBP1 in Chinese glioma population." (PMID 35299889, 2022). "EdU assay showed that ITSN1-L knockdown didn’t manifest significant impact on the proliferation of glioma cells based on PTBP1 silencing, while silencing of ITSN1-L could efficiently reverse the adverse effects of PTBP1 knockdown on glioma cells migration and invasion." (PMID 36171198, 2022). "Only knock-down of PTBP1 lowered the ratio of ITSN1-S/ITSN1-L significantly by remarkably increasing ITSN1-L as well as slightly decreasing ITSN1-S, consistent with the results shown in U87MG and 140 (a primary glioma cell line) cell lines as well as in LN229 cell line." (PMID 36171198, 2022). "Taken together, our study provides a novel mechanism that PTBP1 modulates the alternative splicing of ITSN1 and promotes glioma proliferation and motility by up-regulating the ratio of ITSN1-S/ITSN1-L, thereby highlighting that PTBP1 may be an attractive therapeutic target for gliomas." (PMID 36171198, 2022).
colorectal cancer (45 papers, 2015 to 2025). A primary or metastatic malignant neoplasm that affects the colon or rectum. "It is noteworthy that miR-26a specifically targets a protein essential for colorectal cancer regulation known as pyruvate dehydrogenase X,183 as observed with PTBP1-associated miR-1 and miR-133b in colorectal tumors." (PMID 40028033, 2025). "The elevated expression of PTBP1 in colorectal cancer tissues observed in this study supports its oncogenic role, consistent with previous findings that linked PTBP1 to tumor growth and metastasis in multiple cancers." (PMID 40469179, 2025). "PTBP1 expression has previously been associated with invasiveness in colorectal cancer through alternative splicing of cortactin." (PMID 39010058, 2024). "A recent study found that PTBP1 is overexpressed in ovarian tumors and colorectal cancer, indicating that PTBP1 is closely associated with the pathogenesis and development of cancer." (PMID 35600383, 2022). "RNA sequencing data from GSE229613 indicated that curcumin treatment markedly reduced PTBP1 expression in colorectal cancer cells, though the underlying mechanism remains unknown." (PMID 40469179, 2025). "Together, these results implicated PTBP1 is involved in colorectal cancer progression and may be proposed as a new biomarker of CRC." (PMID 28404950, 2017). "Influences on cell motility caused by PTBP1 maybe due to the splicing events of exon 11 of cortactin gene in colorectal cancer." (PMID 28404950, 2017). "Ectopic expression of PTBP1 abrogated the effects induced by knockdown of LUCAT1, suggesting that LUCAT1 interacted with PTBP1 in colorectal cancer cells and promoted the AS of DNA damage‐related genes." (PMID 40579921, 2025). "For example, in colorectal cancer, PTBP1 can convert PKM1 to PKM2 through selective shearing, promoting the Warburg effect in tumour cells." (PMID 40579921, 2025). "Further studies are warranted to dissect the pathways connecting curcumin, PTBP1, and autophagy in colorectal cancer." (PMID 40469179, 2025). "This study demonstrates that curcumin exerts potent anticancer effects in colorectal cancer through a combination of mechanisms, including the inhibition of PTBP1 and CDK2 activity." (PMID 40469179, 2025). "PCR analysis showed that PTBP1 was significantly overexpressed in colorectal cancer tissues compared to adjacent normal tissues, a finding confirmed by Western blot analysis." (PMID 40469179, 2025). "ChIP-qPCR analysis confirmed c-MYC as a transcriptional regulator of PTBP1 in colorectal cancer cells." (PMID 40469179, 2025). "Investigating the tumor-related mechanisms of PTBP1 is essential, as dysregulation in its expression has been involved in disease promotion, including colorectal cancer invasion, breast and ovarian cancer cell growth, and Parkinson’s disease." (PMID 39057099, 2024). "Particularly in the brain and colorectal cancers, low expression of miR-124 triggers a feedback cascade on PTBP1/PKM1/PKM2, which promotes cancer cell growth." (PMID 38785973, 2024). "AP impedes cellular glycolysis in colorectal cancer cells by obstructing the β-catenin/c-Myc/PTBP1 signaling pathway, thereby inhibiting the activity and expression of tumor-specific PKM2." (PMID 39330497, 2024). "For example, circRHOBTB3 represses metastasis by regulating the HuR-mediated mRNA stability of PTBP1 in colorectal cancer." (PMID 39293372, 2024). "PTBP1 has been reported to be dysregulated in several caners, including gastric, bladder, and colorectal cancers." (PMID 39431006, 2024). "In colorectal cancer, PTBP1 synergistically enhances the formation of circTDRD3 under hypoxic conditions." (PMID 38993556, 2024). "For example, circRHOBTB3 was reported to inhibit colorectal cancer aggressiveness via regulating HuR-mediated PTBP1 mRNA stability." (PMID 37179359, 2023).
colorectal cancer (continued). "KAT2A has been reported to promote carcinogenesis in colorectal cancer by interacting with RNA-binding protein PTBP1 and to modulate cGAS through increasing expression and post-translational modification in systemic lupus erythematosus." (PMID 37047552, 2023). "For instance, circRHOBTB3 can bind with HuR to promote β-Trcp1-mediated ubiquitination of HuR and to reduce the expression level of the downstream target PTBP1 in colorectal cancer." (PMID 37880717, 2023). "A recent study demonstrated that PTBP1 was upregulated under hypoxia and promoted progressions and chemoresistance of colorectal cancer." (PMID 36447254, 2022). "High expression of PTBP1 regulates the alternative splicing of cortactin and promotes the progression of colorectal cancer." (PMID 35600383, 2022). "Polypyrimidine tract-binding protein 1 promotes the development of metastases with colorectal cancer and clear-cell renal cell carcinoma, glioblastoma, and epithelial ovarian tumors." (PMID 33498752, 2021). "For example, hypoxia-induced LUCAT1 contributes to colorectal cancer cell proliferation and chemoresistance via interacting with polypyrimidine tract binding protein 1 (PTBP1)." (PMID 34903711, 2021). "To explore the relation between PTBP1 and cortactin isoform-a, we first detected their mRNA expression levels in colorectal cancer tissues." (PMID 28404950, 2017). "Initially, we found that high expressed PTBP1 and poor prognosis was interrelated in colorectal cancer (CRC) patients with stages II and III CRC, which widely different in prognosis and treatment, by immunohistochemistry." (PMID 28404950, 2017). "We found that PTBP1 displayed the more frequent strong immunoreactivity both in colorectal cancer samples (56.3%, 89/158) and adenomas (77.2%, 34/44) which comparing with normal colon epithelium (10%, 11/106) (P<0.001, respectively)." (PMID 28404950, 2017). "Then after siRNA-mediated knockdown of PTBP1, cortactin isoform-a was significantly decreased in three colorectal cancer cell lines by real-time PCR and RT-PCR but the total mRNA levels of cortactin remained slightly unchanged." (PMID 28404950, 2017). "Overexpressing PTBP2 increased its abundance by enhancing the utilization of its exon 10, which partially neutralized the repressive effect of elevated PTBP1 in colorectal cancer cells." (PMID 26857472, 2016). "This suggests a potential role for PTBP1 in colorectal cancer progression." (PMID 40469179, 2025). "In terms of regulating the mode of cell death, PTBP1 can participate in the regulation of autophagy and apoptosis in colorectal cancer cells through the regulation of downstream target genes, and it was found that PTBP1 activates autophagy by stabilising BECN1 mRNA to promote tumour progression." (PMID 40579921, 2025). "Moreover, PTBP1 can inhibit apoptosis in colorectal cancer cells by regulating the expression of apoptosis key proteins Bax and Bcl2." (PMID 40579921, 2025). "PTBP1 also contributes to colorectal cancer cells metastasis through downregulation of ATG10." (PMID 36949664, 2023). "Here, we found that kaempferol could inhibit the expression of PKM2, the key enzyme of glycolysis, and the three splicing factors of the PKM gene, PTBP1, hnRNPA1 and hnRNPA2, thus reversing the resistance of colorectal cancer cells to 5-Fu." (PMID 35408903, 2022). "PTBP1 was frequently altered in colorectal cancer, pancreatic cancer, and ovarian cancer; PTBP2 was frequently altered in non-small cell lung cancer, lung cancer, and ovarian cancer; and PTBP3 was frequently altered in pancreatic cancer, soft tissue sarcoma, and colorectal cancer." (PMID 36203873, 2022). "LncRNA LUCAT1 could interact with PTBP1 and subsequently facilitate altered alternative splicing of DNA damage related genes in colorectal cancer." (PMID 32677984, 2020).
colorectal cancer (continued). "Consequently, we observe minimal or no reduction in RIPK1 canonical splicing of exon 4 to exon 5, or in resistance to necroptosis, upon PTBP1 knockout in the human colorectal cancer cell lines." (PMID 29449584, 2018). "Also the mRNA levels of PTBP1 and cortactin isoform-a were cooperatively expressed in colorectal cancer tissues." (PMID 28404950, 2017). "Our results showed that PTBP1 is highly expressed in colorectal cancer tissues and colonic cancer cell lines comparing with normal colon tissue and normal human colon cell lines, as demonstrated by the immunohistochemistry and western blot analysis, consisting with previous studies." (PMID 28404950, 2017). "Denovirus shRNA knockdown of PTBP1 inhibited colorectal cancer growth in vivo." (PMID 28404950, 2017). "PTBP1 expression was upregulated both in colon cancer cell lines and primary colorectal cancer." (PMID 28404950, 2017). "Interestingly, we found that two enriched motifs, SRSF2 and U2AF2, were previously reported to be highly involved in AML progression through aberrant splicing regulation and another motif, PTBP1, was shown to play an important role in breast and colorectal cancers." (PMID 29665865, 2018). "Given that PTBP1 may regulate cortactin exon 11 which can be seen in RT-PCR, we performed RNA immunoprecipitation and showed that PTBP1 efficiently coprecipitated cortactin RNA in the colorectal cancer cell line HCT-116, confirming a direct interaction." (PMID 28404950, 2017). "The interaction induced PTBP1 cytoplasmic translocation and stabilized BECN1 mRNA in a PTBP1-dependent manner, thereby promoting colorectal cancer development." (PMID 40790019, 2025). "In non-small cell lung cancer, miR-644a functions as a tumor suppressor to inhibit PTBP1 expression, and in colorectal cancer, HuR binds to the 3’UTR region of PTBP1 to promote PTBP1 stability." (PMID 38785973, 2024). "Kaempferol promotes the expression of miR-339-5p, which in turn, directly targets hnRNPA1 and PTBP1, diminishing the expression of PKM2 and inducing the expression of PKM1, thus inhibiting glycolysis and the growth of colorectal cancer." (PMID 39330497, 2024). "Our findings highlight a regulatory network involving KLF15, LINC00689, PTBP1, LATS2, and the YAP1/β-catenin pathway in colorectal cancer, shedding light on potential therapeutic targets for colorectal cancer therapy." (PMID 38273088, 2024). "In colorectal cancer, PTBP1 is often overexpressed which leads to the alternative splicing of CD44, promoting colorectal cancer progression." (PMID 36508323, 2023). "A recent study reported that the alternative splicing of certain DNA damage-related genes is altered in colorectal cancer cells, following LUCAT1-facilitated interaction of those genes with PTBP1." (PMID 34947843, 2021). "In colorectal cancer cells, hypoxia‐induced lncRNA LUCAT1 interacts with PTBP1 and promotes the binding of a series of DNA damage‐related genes to PTBP1, leading to alterations in the selective splicing of these genes and resulting in chemoresistance in colorectal cancer cells." (PMID 40579921, 2025). "In addition, CDK2 may regulate PTBP1 expression via phosphorylation of c-MYC, suggesting a potential CDK2–c-MYC–PTBP1 signaling axis in colorectal cancer." (PMID 40469179, 2025).